CD4 (CD4 molecule)
Diseases named in the same sentence as CD4 in open-access papers (continued):
Sharing a sentence is not in itself a finding about the gene and the disease.
infection (continued). "Retinoic acid is also required to elicit pro-inflammatory CD4+ T cell responses to infection and mucosal vaccination, since blocking retinoic acid receptor signaling results in a cell-autonomous impairment in CD4+ T cell activation." (PMID 33679800, 2021). "Measuring the kinetics of the fusion in CV-1 derived CD4 expressing cells showed that 50% of fusion events occurred ~13 min after the onset of the infection (by temperature shift from 4 °C to 37 °C)." (PMID 33573241, 2021). "In the absence of IFNγ or IL-23p19 the numbers of activated CD62LloCD44hi CD4+ cells in the alveolar spaces were elevated over the wildtype mice at day 31 post-infection." (PMID 34682248, 2021). "Despite larger titers of viruses recovered from the lung, infection with viruses expressing shutoff active NS1 (Cal[NS1_high-PAX_low] or Cal[NS1_high-PAX_high]) resulted in significantly fewer IAV-specific CD4+ and CD8+ T cells in the MLN and spleen at 7 dpi." (PMID 34200539, 2021). "In C57BL/6 mice, vaccination increased the percentage of effector memory CD4 T cells at weeks 3 and 6 post-infection." (PMID 34351501, 2021). "A subset of CD4+ clones were identified in pre-infection central memory subsets, and a subset of CD8+ T cells were found in effector memory." (PMID 33399535, 2021). "Of these 180 individuals, 47 had low CD4 count (< 200 cells/mm3) and they were therefore reclassified as having long-term infection according to RITA, leaving 133 individuals classified as recently infected." (PMID 33653290, 2021). "Viruses such as SARS and HIV‐1 use these receptors to capture DCs and through a trans‐infection mechanism transmitting to other target cells, especially promoting a vigorous infection of CD4+T cells." (PMID 34028178, 2021). "In B6.Il10-/- mice, L. donovani infection induced a faster but transient activation of bone marrow monocytes, which correlated with the magnitude of CD4+ T cell production of IFNγ and resolution of the infection." (PMID 34557190, 2021). "Patients coinfected with S. stercoralis and HTLV-1 have increased proportions of CD4+CD25+FoxP3+ regulatory T-cells compared to patients with either infection alone, and these proportions are inversely correlated with antigen-driven IL-5 responses." (PMID 34314415, 2021). "Remarkably, our results show that IL-33 treatment during CR infection reduced the frequencies of IL-17A-expressing CD4+ T cells within the infected colon, and the impaired IL-17A response correlated with the uncontrolled pathogen clearance." (PMID 33654214, 2021). "Median CD4+ T counts for individuals treated with ART during hyperacute infection were 848 and 907 cells/mm3 at 1- and 12-months respectively, which was not significantly different from the median count of 1,045 cells/mm3 for HIV uninfected individuals." (PMID 34630420, 2021). "Paradoxically, this yielded approximately a 2-fold decrease in productive infection in target CD4 T cells 48 h post-infection." (PMID 34578310, 2021). "Since MAP remains within macrophages and other infected cells, the host immune system organizes a prolonged immune response with activated cytotoxic T cells, γδ T cells, CD4 cells, and cytokines, leading to granuloma formation and diffusion of the infection." (PMID 34290737, 2021). "In the early stages of infection, infected adults had significantly higher CD4+ T cell responses to viral structural/ORF1ab proteins but CD8+ T cell responses were unremarkable." (PMID 34326343, 2021). "As a result, we were unable to use monoclonal antibody depletion in the context of the persistent UgCl223 infection to examine the role of CD4 T-cells in the lungs." (PMID 35186781, 2021). "Diagnosis several years after an infection led to declining levels of CD4 + cells at the time of sampling." (PMID 34400726, 2021). "IL-27Rα−/− CD4 T cells were more glycolytic, suggesting that IL-27 seems to limit Th1 cell glycolysis to further protect against tissue pathology during infection." (PMID 34045653, 2021).
infection (continued). "In fact, when comparing these five donors to the five infection-naïve donors, there was a significant decrease in the magnitude of the spike-specific CD4+ T cell response, while the spike-specific CD8+ T cell response was equivalent between the two groups." (PMID 34636722, 2021). "By analyzing the correlation between CD4+ T cells and duration of infection, SIVmac239-infected NPMs showed continuous disease progression in the chronic stage." (PMID 34630335, 2021). "In vivo infection of CD4–TREM-2 conditional knockout mice with murine coronavirus mouse hepatitis virus A-59 showed that intrinsic TREM-2 in T cells enhanced TH1 response and viral clearance, thus aggravating lung destruction." (PMID 34878838, 2021). "Analysis of lymphocyte populations within lesion and in popliteal lymph node showed that GF mice had similar numbers and frequencies of B, CD8+ T, CD4+ T and regulatory T lymphocytes along the course of infection." (PMID 34745100, 2021). "Resolution of the infection is mediated by Th2 and Tfh CD4+ cells, which provide help for efficient protective antibody production." (PMID 34696180, 2021). "In the blood, both CD4+IFN-γ+ Th1 and CD4+IL-4+ Th2 populations were observed early, but gradually decreased over the course of infection." (PMID 34452011, 2021). "Reciprocally, termination of infection coincides with loss of PD-1 and CTLA-4 expression on HCV-specific CD4 T cells and upregulation of the memory cell marker CD127." (PMID 34452460, 2021). "We now know that, although a large majority of CD4+ T cells that are infected by HIV in vivo die within a few days of infection, a small fraction of the infected cells survive and divide, producing large clones, with important clinical consequences." (PMID 34696507, 2021). "In fact, the profile of several miRNAs in plasma are differently expressed in chronically infected individuals and correlate with CD4+ T cell count or with the known time of infection." (PMID 34451482, 2021). "Our data showed that upon anti-IL-2 mAb administration, mice had fewer CD4+CD25+Foxp3+ T cells at day 21 post-infection." (PMID 34869064, 2021). "b., leukocyte and CD8 T cell levels in the brain parenchyma during the late stage of infection of cd4-/- and WT mice were also similar." (PMID 34587172, 2021). "This is supported by data from Dan and colleagues, showing a trend toward an increase of SARS-CoV-2-specific CD4+ follicular helper T cells, a specialized subset of CD4+ T cells required for B cell help, six months after infection." (PMID 33723016, 2021). "In acute infection, CTLs deplete HIV-1 infected CD4+ T cells, allowing CTLs to partially control the infection." (PMID 33897659, 2021). "In the absence of fibroblasts, the transwell system resulted in higher infection rates than our regular culture conditions where transwells were not used, likely because of increased cell-to-cell contact between CD4+ T cells in the transwells." (PMID 33976386, 2021). "We conclude from these data that B lymphocytes, activated by two surrogates for CD4+ T helper cells, i.e., IL-4 and CD40L, are more efficient than myeloid DC in mediating HIV-1 trans infection of activated CD4+ T lymphocytes." (PMID 33688006, 2021). "There was a significant rise in the expression levels of both HAL and HDC 48 h post infection, in macrophages activated with CD4 T cells or treated with external IFN-γ." (PMID 33767335, 2021). "Once an infection has resolved, resident memory CD4 Th1 cells in the skin, central memory CD4 T cells and circulating effector CD4 Th1 cells maintained by persistent parasites provide protection against a secondary challenge." (PMID 33841444, 2021). "In comparison, small-scale experiments with mock control CD4+-T cells showed substantially higher transduction rates with HIVenv-pseudotyped lentiviral vectors (12.7–26.3%) at identical multiplicity of infection." (PMID 33867524, 2021).
infection (continued). "The CD4 cell count of patients during diagnosis and distribution of CD4 cell counts in the patient population are important to understand infection-diagnosis interval and incidence rate of human immunodeficiency virus (HIV) infection, respectively." (PMID 34511561, 2021). "This highlights CSF CXCR5+CD4 T cells a key target and potential missing link to the poorly understood phenomenon of intrathecal B cell and antibody responses with relevance for infection control, chronic inflammation and CNS autoimmunity." (PMID 34446066, 2021). "In summary, VACV blocks skin DC mobilization from the site of infection while retaining the ability to access the dLN to prime CD4+ T cells." (PMID 33419767, 2021). "In particular, failure to maintain HCV-specific CD4 T cell help is a principal feature of infections that eventually persist." (PMID 34452460, 2021). "The protective capacity of CD4+ T cells has been demonstrated in murine infection models of SFG as well as of TG rickettsiae." (PMID 34452021, 2021). "Duration of infection and aviremia, nadir CD4, pretherapeutic viral load and CD4:CD8 ratio, as well as age were not different between Profile E and the other Profiles." (PMID 33859653, 2021). "In contrast, Siglec-1 trans-infection takes advantage of activation signals provided by DCs to CD4+ T cells, which promote active infection of target cells as suggested by the preferential infection of HIV-1-specific CD4+ T cells." (PMID 35055987, 2021). "We examined if LEC MHC-II and its regulation of CD4+ TRM cell activities instructs innate immune cellular responses to memory recall infections." (PMID 34611166, 2021). "In the CD8-depleted group, CD4+ T responses to the second infection appeared slightly stronger than in controls, possibly as a compensatory response to the lack of CD8+ T cells." (PMID 34452011, 2021). "To test this, we compared the fold change in colonic CD4 T-cell populations during acute SIV/SHIV infection to the levels of viral burden following cART." (PMID 34452474, 2021). "Conceptually, T cells do not recognize the virus but only recognize virus-infected cells (CD8 T cells) or cells that have internalized viral antigens produced after infection (CD4 T cells)." (PMID 34471260, 2021). "The main target cells in early infection are mucosal CD4+ T cells, which are activated, have high expression levels of both CD4 and CCR5, and are depleted during HIV infection." (PMID 33594125, 2021). "For this, mice were challenged with M.tb (about 200 CFU/mice) by aerosol route, and after 30 days of infection, CD4+ T cells were transferred from M.tb-infected WT mice to KO mice." (PMID 34899731, 2021). "In contrast, we observed that the transfer of HIV sheltered in InR platelets to macrophages is productive, as infection spreads replication-competent virus to healthy donor’s reporter CD4+ T cells (right)." (PMID 35222352, 2021). "In this PKO murine model of persistent infection, they found that NK cells and CD4+ T cells produced high levels of IL-10 GFP for a longer time (until day 8 post-infection)." (PMID 35053151, 2021). "These regulation of parasite antigen-specific IL-19 and IL-24 expressing CD8+ T cells are more dependent on the stage of the infection than on IL-10, IL-1β, and IL-23 as observed in the regulation of CD4+ T cell response." (PMID 34603287, 2021). "Our standard neutralization assay uses pNL-LucR-E- and an Env plasmid to make PV for infection of CF2.CD4.CCR5 cells." (PMID 34679128, 2021). "CD4 decay differed by stage of infection at diagnosis and age, with those ≥50 years in Stages 1 and 2 experiencing a faster decline in CD4 over time." (PMID 33577551, 2021). "Nevertheless, the role of CD4 T cells, particularly Th17 cells, in the antifungal immunity to T. marneffei still needs to be further investigated by using IL-17A knockout mice infection models." (PMID 34912336, 2021).
infection (continued). "After adjusting for age, B.1.1.7 variant infection was a risk factor for elevated CRP (P = 0·045), SAA (P = 0·011), CK (P = 0·034), and CD4+ T (P = 0.029) and for the presence of GGO (P = 0.005)." (PMID 34346755, 2021). "HLA-DRB1*04 is classified as MHC class II, which presents antigens to CD4+ T cells at the site of infection." (PMID 34963463, 2021). "Other studies have also reported that subsets of elite controllers develop overt viremia and CD4+ T-cell decline over the course of infection." (PMID 33804076, 2021). "T cells in the groups immunized with rgH3N2 or rgH3N2 4xM2e were effectively depleted by delivering either anti-CD4 or anti-CD8 or both antibodies prior to infection with A/Phil (H3N2, 17 LD50)." (PMID 33603072, 2021). "Long-term maintenance of these responses, particularly CD4 T cell help, is strongly correlated with spontaneous resolution of infection, which occurs in approximately 30% of HCV-naïve individuals." (PMID 34452460, 2021). "During the primary phase of infection, the virus targets AT directly (by infecting AT CD4 T cells) and indirectly (via viral protein release, inflammatory signals, and gut disruption)." (PMID 34220817, 2021). "Infection rates remained low for CD4-VLPs at both concentrations, suggesting that a therapeutic that presents clusters of CD4 is more effective than traditional CD4-based inhibitors in controlling HIV-1 replication and preventing viral escape." (PMID 32690692, 2020). "We previously published that both CD4 depletion and SIVmac251 infection during LTBI resulted in reactivation rates of 50% (within 12 weeks) and 100% (50% by 8 weeks and 100% by 48 weeks after SIV), respectively." (PMID 32730321, 2020). "Results for PWID were also affected by the use of default CD4 assumptions or the Danish CD4 proxy, although in both models the 95%CIs were wide and estimates of new infections and number undiagnosed in 2018 low." (PMID 32590964, 2020). "This study found that over 4–14 days T/F viruses replicated to higher titers in T cells than in macrophages, suggesting that T/F viruses have a greater capacity for infection of T cells, which express high levels of CD4." (PMID 32726944, 2020). "To evaluate variations in immune response according to KoRV subtype infection status, we measured expression levels for CD4, CD8b, IL-6, IL-10, and IL-17A in RNA isolated from unstimulated koala PBMCs." (PMID 33316950, 2020). "Due to the lack of knowledge on T-cell mediated immunity in pigs in response to STM infections, we studied the antigen-specific CD4+ T-cell immune response of swine, both locally and systemically." (PMID 33584671, 2020). "However, HIV may also cause reduced production of naïve T cells by infection of CD4+ thymocytes." (PMID 32154191, 2020). "These women were recruited before early treatment became the standard of care in South Africa, when treatment was based on CD4 cell number, and thus these women were untreated over the first year of infection." (PMID 32849622, 2020). "Although CD4+ T cell memory is a critical component of adaptive immunity, antigen-specific CD4+ T cell recall responses to secondary infection have been inadequately studied." (PMID 32983171, 2020). "Nodes for 640 and 837 were directly connected within the founder B subnetwork most related to CD4 and R5 binding, so both of these positions likely have strong roles in establishing infection." (PMID 33284837, 2020). "By day 30 after infection, the CD4+ TRM cells become the main population of IL-17-producing T cells that react to C. albicans." (PMID 33633737, 2020). "Here, adoptively transferred immune CD4+ T cells still protected the mice even when transferred late in the infection when the bacteria already start to grow." (PMID 33091016, 2020). "Once bound to CGs, CD4 cannot interact with gp120, preventing infection of CD4-positive T cells by HIV." (PMID 32825645, 2020).
infection (continued). "Expansion and maintenance of memory CD8+ T cells are CD4+ T‐cell‐dependent in numerous infection models, with data supporting an essential role of CD4+ T cells in aspects of initial memory CD8+ T‐cell priming through factors such as CD27 and CD40 signalling." (PMID 33005416, 2020). "That CD4+ T cells alone are sufficient to mediate protection against the infection with R. typhi is further demonstrated by adoptive transfer of immune CD4+ T cells into susceptible T and B cell–deficient C57BL6 RAG1-/- mice." (PMID 33091016, 2020). "Similar to our results in THP-1 and primary CD4+ T cells, infection with the HIV-1 N74D capsid mutant can be rescued by knockdown of either TRIM34 or TRIM5α in MoDCs." (PMID 32282853, 2020). "This is supported by Fidel (2006), who suggests that Candida specific T cells do not become defective with immunosuppression, but a threshold number of CD4 cells are required to protect the oral cavity against infection by this normal commensal." (PMID 32774600, 2020). "(B) FACS analysis of GFP expression in activated primary CD4+ cells after infection with V1/δ-Vpr or V1/HA-Vpr." (PMID 32538781, 2020). "DCs perform an essential role in the transmission of HIV-1 to target CD4+ T cells, promoting the spread of infection." (PMID 32075937, 2020). "From at least 3 months of infection, the ALP's positive linear association with the CD4+ count diminishes beyond the normal ALP upper limit of 120 IU/L but still supporting the CD4+ count to above average." (PMID 32190387, 2020). "Prior to the vaccination phase of the experiment, two groups of eight RMs were balanced for sex, age at infection, peak viral load, CD4+ T cell frequency at ART initiation, and AUC of pre-ART viremia." (PMID 33104758, 2020). "Transduction with AGT103 showed strong, dose-dependent protection of CD4 T cells against infection with HIV NL4.3." (PMID 32462053, 2020). "To study this, we developed a cell transfer-based approach to identify differences between memory and naïve CD4+ T cells specific for C. trachomatis following secondary infection." (PMID 33091023, 2020). "We found that knockout of YTHDF3 in human CD4+ T-cells increases infection supporting the role of YTHDF3 as a restriction factor." (PMID 32053707, 2020). "Finally, central memory, naïve and stem cell memory CD4+ T cell subsets were susceptible to infection, albeit inefficiently by Envs from all time-points, suggesting that direct infection of these cells may help establish the latent reservoir early in infection." (PMID 32762760, 2020). "Upon infection with HSV-2, the risk of acquiring HIV is tripled due to induction of the immune response in the genital tract, which leads to more CD4 T cells that express the CCR5 receptor, which is involved in HIV transmission and infection." (PMID 32727077, 2020). "Mucosal immunization of mice with BCG induces a higher frequency of CD4 TRM cells in the lungs when compared with immunization by a parenteral route, and this is associated with enhanced protection against infection in the lungs." (PMID 33096737, 2020). "Pre-exposure of DC to hemozin promoted HIV-1 transfer to CD4+ T cells, while protecting DC from productive infection with the virus." (PMID 32354203, 2020). "An analysis of mTOR activity in virus-specific CD4 T cells revealed a similar dynamic pattern: mTOR signaling reaches a peak at day 2 postinfection and drops to a baseline level at day 8 after infection." (PMID 32999031, 2020). "Their results show a more severe and prolonged acute phase of infection in diabetic mice, with impaired CD4+ T cell recruitment to the lungs and altered cytokine profiles, such as elevated IL17." (PMID 32612666, 2020). "The adaptive immune response to infection by NTS such S. Typhimirium starts with an early DC-mediated activation of pathogen-specific CD4 T cells limited to the Peyer's patches and the mesenteric lymph nodes." (PMID 33042146, 2020).